CUTA (cutA divalent cation tolerance homolog)
Description:
May form part of a complex of membrane proteins attached to acetylcholinesterase (AChE).
Synonyms: ACHAP; C6orf82
Tractability: Small molecule: it has a binding pocket of medium quality. Antibody: UniProt predicts a signal peptide or a membrane-spanning region; the Human Protein Atlas places it where antibodies can reach. PROTAC: ubiquitination databases record sites on it; its protein half-life has been measured.
Gene: Protein-coding gene on chromosome 6 (33,416,442 to 33,418,381, reverse strand). Ensembl gene ENSG00000112514.
Subcellular location (Human Protein Atlas): Focal adhesion sites; Plasma membrane; Predicted to be secreted
Gene Ontology:
Molecular function: enzyme binding; protein binding
Biological process: intracellular protein localization; response to metal ion
Cellular component: extracellular exosome; membrane; mitochondrion
Genetic constraint (gnomAD): Loss-of-function variants: 24 observed, 24.86 expected, observed/expected ratio (o/e) 0.97, 90% interval 0.7 to 1.36. The upper end of that interval is the gene's LOEUF score, 1.36, which puts it in group 5 of 6, group 1 being the genes least tolerant of losing a copy. Missense variants: 227 observed, 235.59 expected, observed/expected ratio (o/e) 0.96, 90% interval 0.86 to 1.08. Synonymous variants: 94 observed, 100.76 expected, observed/expected ratio (o/e) 0.93, 90% interval 0.79 to 1.11.
Homologues: Orthologues: macaque CUTA (98% identical), dog CUTA (90% identical), mouse Cuta (89% identical), pig CUTA (89% identical), rabbit CUTA (88% identical), chimpanzee CUTA (86% identical), guinea pig CUTA (84% identical), rat Cuta (56% identical), tropical clawed frog cuta (50% identical), Drosophila melanogaster CG11590 (37% identical), Caenorhabditis elegans F35G12.7 (25% identical).
Diseases named in the same sentence as CUTA in open-access papers:
CUTA is named in the same sentence as 9 diseases in open-access papers, as found by Europe PMC text mining. Sharing a sentence is not in itself a finding about the gene and the disease. The quoted sentences say what the papers report.
Alzheimer disease (1 paper, 2024). A progressive, neurodegenerative disease characterized by loss of function and death of nerve cells in several areas of the brain leading to loss of cognitive function such as memory and language. "Since CUTA is predicted to be a mitochondrial protein and is usually connected with Alzheimer’s disease, there are some new observations about its overexpression in the cancer tissue." (PMID 39000458, 2024).
autism (1 paper, 2022). Persistent deficits in social interaction and communication and interaction as well as a markedly restricted repertoire of activity and interest as well as repetitive patterns of behavior.
rheumatoid arthritis (1 paper, 2012). A chronic, systemic autoimmune disorder characterized by inflammation in the synovial membranes and articular surfaces. "CutA may play a role in the pathogenesis of Alzheimer’s, however, its role in rheumatoid arthritis remains to be elucidated." (PMID 23259760, 2012).
infection (1 paper, 2019). The state of being infected such as from the introduction of a foreign agent such as serum, vaccine, antigenic substance or organism. "In B. cinerea, this family included the cutA gene previously shown to be expressed in tomato fruit infection." (PMID 30881367, 2019).
CUTA also shares sentences with these, for which no sentence is quoted: cancer (2 papers); Achalasia (1); breast carcinoma (1); neurodevelopmental disorder (1); schizophrenia (1).